ZIC5 (Zic family zinc finger 5)
Diseases named in the same sentence as ZIC5 in open-access papers (continued):
Sharing a sentence is not in itself a finding about the gene and the disease.
tumor (continued). "Analysis of tumor immune infiltration showed the elevated expression levels of IGF2BP3, DPCR1, HOXD10, TRIM7, and ZIC5 tended to be correlated with the increased tumor infiltrating B cells, CD8+ T cells, CD4+ T cells, and APCs including macrophages and DCs in COAD patients." (PMID 35593226, 2022). "Among the most overexpressed genes in tumor cells compared to normal tissue were the transcription factors HOXB9, SIM2, ZIC5, SP8, TFAP2A, FOXE1, HOXB13, and SALL4; the cancer testis antigen CT83; and the cytokine IL23A." (PMID 37228492, 2023). "However, whether ZIC5 overexpression contributes to tumor metastasis in PCa remains unclear." (PMID 36127329, 2022). "Taken together, these results suggested the prognosis‐related tumor antigens including IGF2BP3, DPCR1, HOXD10, TRIM7, and ZIC5 were promising targets of being developed as mRNA vaccines against COAD." (PMID 35593226, 2022). "A total of five selected tumor antigens, including IGF2BP3, DPCR1, HOXD10, TRIM7, and ZIC5 were identified as promising candidates for mRNA vaccine." (PMID 35593226, 2022). "A total of five tumor antigens with prognostic values were identified, including IGF2BP3, DPCR1, HOXD10, TRIM7, and ZIC5." (PMID 35593226, 2022). "In the mRNA group, ZIC5, C12orf75, C1QL1, TMEM74, and GNAZ were significantly upregulated in tumor tissues compared to the adjacent control; PZP and FAM65C were significantly downregulated compared to the adjacent control." (PMID 31156698, 2019). "Among the most overexpressed genes in tumor cells compared to normal tissue are genes coding for transcription factors (HOXB9, SIM2, ZIC5, SP8, TFAP2A, FOXE1, HOXB13, and SALL4), cancer testis antigens (CT83), and cytokines activating regulatory Th17 cells (IL23A)." (PMID 37228492, 2023). "Lastly, in the young.tumor versus old.tumor contrast, we identified five DEGs (ZIC2, ZIC5, ZNF439, USP54, and C2); this contrast may reflect differences in intrinsic tumor properties between tumors from the two age cohorts." (PMID 28027300, 2016).
cancer (11 papers, 2016 to 2025). A tumor composed of atypical neoplastic, often pleomorphic cells that invade other tissues. "ZIC5, for instance, is upregulated in several malignancies, suggesting its potential as a diagnostic marker in those types of cancers." (PMID 40952541, 2025). "Moreover, methylation level of cg12821539 was positively correlated with expression of ZIC5 (rho=0.62), which has been implicated as oncogenes in some cancers." (PMID 37293596, 2023). "ZIC5 expression is enhanced in patients with various types of cancer and is related to poor prognosis, whereas ZIC5 expression is barely observed in most normal human adult tissues." (PMID 40318167, 2025). "Apart from SOX2, other genes involved in cancer aggressiveness, such as ZIC5, FAM83A, AADAC and MYEOV, were among the top most significantly associated genes and were associated with patient outcome." (PMID 36932385, 2023). "Accumulating evidence shows that ZIC5 is dysregulated in various cancers and correlates with outcome and prognosis of patients." (PMID 36127329, 2022). "Given that EMT is a major step in the process of cancer cell metastasis, and ZIC5 was reported to modulate the expression of EMT genes." (PMID 36127329, 2022). "Using a cut-off of ≥ 1%, protein expression of ZIC5 was present in 28% GS < 7, 43% GS 7 and 57% GS > 7 cancer (p < 0.001)." (PMID 27191985, 2016). "Besides its important role in organ development, studies in recent years suggested that ZIC5 is involved in the pathology of various diseases, including cancer, and highlighted also some potential mechanisms." (PMID 36127329, 2022). "Thus, ZIC5 enhances survival signaling and drug resistance in various types of cancer." (PMID 40318167, 2025). "Interestingly, elevated expression of ZIC5 has been observed in various human cancers and may contribute to cancer progression." (PMID 34830820, 2021). "We utilised the UALCAN platform to examine the transcription levels of ZIC5 in both LUAD and LUSC cohorts and investigated its potential impact on OS in cases involving these cancer types." (PMID 40344305, 2025). "We identified 30 cancer-specific normal-invariant genes, including Zic family members (ZIC1, ZIC4, and ZIC5), DPPA2, PRSS56, ELF5, and FGF18, most of which were cancer-associated genes." (PMID 39969322, 2024). "Zinc finger of the cerebellum 5 (ZIC5), a transcription factor belonging to the ZIC family, is involved in the pathology of various cancers." (PMID 36127329, 2022).
adenocarcinoma (1 paper, 2025). A common cancer characterized by the presence of malignant glandular cells. "Study findings indicate a distinct upregulation of ZIC5 in LUAD relative to LUSC, with adenocarcinoma cases presenting significantly increased ZIC5 expression that specifically associates with adverse survival probabilities." (PMID 40344305, 2025).
ZIC5 also shares sentences with these, for which no sentence is quoted: clear cell renal cell carcinoma (1 paper); glioblastoma (1); lymphoma (1); medulloblastoma (1); non-small cell lung carcinoma (1).